CELF1 (CUGBP Elav-like family member 1)
Diseases named in the same sentence as CELF1 in open-access papers (continued):
Sharing a sentence is not in itself a finding about the gene and the disease.
Alzheimer disease (5 papers, 2016 to 2024). A progressive, neurodegenerative disease characterized by loss of function and death of nerve cells in several areas of the brain leading to loss of cognitive function such as memory and language. "Finally, genome-wide studies revealed an association between CELF1 locus and Alzheimer disease suggesting putative relationships between CELF1 and neurodegeneration." (PMID 27222809, 2016). "Additionally, while some studies have identified associations between CELF1 and non-cancerous diseases such as diabetes, Alzheimer's disease, and obesity, the exact molecular mechanisms underlying its regulatory role in these diseases still require further investigation." (PMID 38443798, 2024).
cardiac hypertrophy (5 papers, 2011 to 2024). "Furthermore, aberrant expression of CELF1 has been implicated in the development of cardiac hypertrophy." (PMID 38443798, 2024). "Induction of CELF1 transgene expression in mouse skeletal muscle was sufficient to reproduce muscle wasting, defective motor performance and myopathy; while CELF1 upregulation in heart caused cardiac conduction defects, cardiomyopathy with hypertrophy and early mortality." (PMID 30050493, 2018). "Cardiac hypertrophy, survival, and alternative splicing of CELF targets were all rescued by crossing MHC-CELFΔ mice to mice over-expressing CELF1 in the heart, indicating that both the molecular and gross phenotypes can be attributed to loss of CELF activity." (PMID 21541285, 2011). "CUG triplet repeat-binding protein 1 (CELF1) was upregulated in mouse hearts upon pressure overload induced by transverse aortic constriction (TAC), while CELF1-KO mice exhibited attenuated cardiac hypertrophy and fibrosis, and improved cardiac function upon pressure overload." (PMID 38132114, 2023).
diabetes (5 papers, 2016 to 2024). "In the context of cardiovascular diseases, especially those exacerbated by diabetes, the role of RBPs such as CELF1 becomes more pronounced." (PMID 39334823, 2024). "Understanding the regulation of RBPs like CELF1 in various pathological conditions could pave the way for innovative therapeutic strategies to address the cardiovascular challenges posed by diabetes." (PMID 39334823, 2024). "In the future, we hope the targets of CELF1 regulation identified here may prove useful for the design of new therapies to prevent or ameliorate cardiomyopathy in patients with DM1 or diabetes." (PMID 26866591, 2016). "Previous studies showed that CELF1 is up-regulating in the hearts of T1DM mice, but diabetes-induced AS alterations are consistent with CELF1 depletion or decreased CELF1 splicing activity." (PMID 36277184, 2022).
dilated cardiomyopathy (5 papers, 2019 to 2023). Cardiomyopathy which is characterized by dilation and contractile dysfunction of the left and right ventricles. "CELF1 upregulation due to abnormal PKC signaling has also been observed in a DM1 mouse model with dilated cardiomyopathy and arrhythmia." (PMID 37791351, 2023). "Furthermore, in another model of dilated cardiomyopathy, CELF1 was found to regulate GJA1 mRNA degradation through an interaction with the nuclear-specific exoribonuclease RRP6, leading to Cx43 downregulation." (PMID 37791351, 2023). "Mice overexpressing CELF1 in the heart show conduction abnormalities and dilated cardiomyopathy thus confirming the contribution of MBNL1 sequestration and CELF1 up‐regulation to DM1 pathogenesis." (PMID 36852954, 2023).
lung squamous cell carcinoma (5 papers, 2015 to 2025). "In cisplatin‐resistant lung squamous cell carcinoma (SCC) cells, reduced levels of miR‐181a‐5p have been linked to the increased expression of the oncogene CUGBP Elav‐like family member (CELF1)." (PMID 41001946, 2025). "The miR-181a-5p/miR-382-5p/CELF1 axis is pivotal in regulating cisplatin resistance in lung squamous cell carcinoma." (PMID 39401197, 2024). "The study showed that TUG1 could bind to PRC2 at the promoter region of CELF1 and negatively regulate CELF1 expressions in lung squamous cell carcinoma H520 cells." (PMID 38473229, 2024).
non-small cell lung carcinoma (5 papers, 2016 to 2021). A group of at least three distinct histological types of lung cancer, including non-small cell squamous cell carcinoma, adenocarcinoma, and large cell carcinoma. "Thus, CELF1 overexpression is linked to disease stage, differentiation, and a poor prognosis in individuals with non-small-cell lung cancer." (PMID 34681716, 2021). "The results are the same in non-small-cell lung cancer, where the downregulation of CELF1 induces an increase in the protein levels of cyclin D1, BAD, BAX, Jun D, and E-cadherin, indicating a function for CELF1 in the EMT (epithelial to mesenchymal transition)." (PMID 34681716, 2021). "Thus, TUG1/EZH2/EED complex inhibits the proliferation of non-small cell lung cancer by binding to the promoter of CUGBP and Elav-like family member 1 (CELF1) and repressing it." (PMID 33050646, 2020).
cardiomyopathy (4 papers, 2013 to 2018). A disease of the heart muscle or myocardium proper. "Either inhibition of CELF activity or over-expression of CELF1 in heart muscle causes cardiomyopathy in transgenic mice." (PMID 26866591, 2016). "Over-expression of CELF1 in heart muscle recapitulates many of these splicing defects and induces cardiomyopathy in transgenic mice." (PMID 26866591, 2016). "The identification of transcripts and pathways that are subject to CELF1 regulation in heart muscle is an important step towards understanding its role in cardiomyopathies." (PMID 26866591, 2016). "Although the effects on cytoplasmic targets of CELF1 have not been investigated in these cardiomyopathies, dysregulation of CELF1-dependent translation is known to contribute to skeletal muscle pathology in DM1." (PMID 26866591, 2016). "When Celf1 is re-induced in adults it is unclear which transcriptional and posttranscriptional changes are directly driven by Celf1 rather than an indirect effect of cardiomyopathy." (PMID 27759042, 2016).
melanoma (4 papers, 2017 to 2024). A malignant, usually aggressive tumor composed of atypical, neoplastic melanocytes. "Previous studies have shown that CELF1 is early induced as an RBP in melanoma cells and biopsies, indicating its potential as a key driver in cutaneous melanoma." (PMID 38443798, 2024). "Previously, CELF1-bound melanoma-enriched transcripts, including the oncogene DEK, were discovered using systems analysis, and CELF1 has been described as a risk factor for overall patient survival." (PMID 34681716, 2021). "It should be noted that while this study focuses on CELF1, RNA-Seq and the oligo-arrays described here identified multiple RBPs upregulated in melanoma cells." (PMID 29269732, 2017). "B the allelic status of CELF1 was largely similar to 13 flanking genes at chromosome 11p11.2 band, as defined by exploring TCGA melanomas." (PMID 29269732, 2017). "Together, these results identify CELF1 as an early-induced RBP during melanoma progression and as a putative adverse indicator of patient prognosis." (PMID 29269732, 2017). "This reduced proliferation was also evident in long-term colony assays performed in various melanoma cell lines after CELF1 depletion by shRNA or by siRNA." (PMID 29269732, 2017). "Here we identify a cluster of melanoma-enriched genes under the control of CUGBP Elav-like family member 1 (CELF1)." (PMID 29269732, 2017). "Proteomic, transcriptomic, histological and functional analyses, together with studies of patient prognosis revealed new roles and melanoma-enriched targets of CELF1, which provide insight on selective RBPs fueling tumor development." (PMID 29269732, 2017). "CELF1 was discovered with a distinct prognostic value in melanoma after mining the genomic landscape of the 692 known mRBPs across different cancer types." (PMID 29269732, 2017). "Together, these data confirm the GU-rich preference for sequence recognition of CELF1, but also emphasize a restricted and melanoma-selective subset of binding targets." (PMID 29269732, 2017). "A corollary of our findings on the CELF1–DEK functional interplay is that both genes should be positively correlated in human melanoma biopsies." (PMID 29269732, 2017). "Instead, the combination of transcriptomic and proteomic analyses (RIP-seq, RNA-Seq and iTRAQ) identified a key role of CELF1 in the stabilization of a distinct and specific set of mRNAs in melanoma." (PMID 29269732, 2017). "Instead, using computational analyses, genome-wide RNA sequencing and customized oligo arrays, we identified CELF1 within a selective set of mRBPs regulated in melanoma cells specifically at the mRNA level." (PMID 29269732, 2017). "Further analyses of the melanoma TCGA specimens stratified for tumor stage suggested an early induction of CELF1 mRNA during melanoma progression." (PMID 29269732, 2017). "CELF1 was identified as a key regulator for melanoma-enriched pro-oncogenic networks." (PMID 33304907, 2020). "Next, published genome-wide analyses of CELF1-bound transcripts were mined to assess additional targets of this protein which we could use as a guideline in melanoma." (PMID 29269732, 2017). "However, only high CELF1 mRNA expression significantly correlated with poor prognosis of primary melanoma patients in this set." (PMID 29269732, 2017). "The “melanoma-only” CELF1 RIP-Seq transcripts were then analyzed to determine whether they could represent a signature enriched in this malignancy." (PMID 29269732, 2017). "To further define the rationale for the selection of CELF1 as a novel pro-tumorigenic RBP in melanoma, we set to assess whether its upregulation was specific or reflected global amplifications of the chromosomal locus where this gene maps." (PMID 29269732, 2017). "Thus, while over half of protein coding genes in the human genome contained GREs that could represent putative CELF1 recognition sites, only 12% of these transcripts were bound by CELF1 in melanoma." (PMID 29269732, 2017).
melanoma (continued). "Together, these data identify a new distinct link between a RBP (CELF1) and an oncogene (DEK) in the control of DNA synthesis and cell cycle progression modulators in melanoma." (PMID 29269732, 2017). "Here, the authors identify RBPs differentially regulated in melanoma, and show the RBP CELF1 controlling a distinct set of protumorigenic factors." (PMID 29269732, 2017). "CELF-1 regulated pathways at protein and RNA levels were then integrated with the RIP-Seq data to define direct vs. indirect targets of CELF1 in melanoma cells." (PMID 29269732, 2017). "Importantly, CELF1 and DEK were found to represent early-induced melanoma genes and adverse indicators of overall patient survival." (PMID 29269732, 2017). "Interestingly, the CELF1–DEK overlap in these systems (21 and 25%, respectively) was approximately half of that in melanoma cells." (PMID 29269732, 2017). "However, we found only 5% of genes undergoing alternative splicing in CELF1-depleted melanoma cells, and no significant accumulation of death regulators." (PMID 29269732, 2017). "CELF1 was identified as a top-scoring factor among RBPs with no previous links to melanoma." (PMID 29269732, 2017).
muscular dystrophy (4 papers, 2011 to 2025). Muscular dystrophy (MD) refers to a group of more than 30 genetic diseases characterized by progressive weakness and degeneration of the skeletal muscles that control movement. "Consistent with the muscular dystrophy model, Mbnl1 mRNAs levels were typically elevated 2–3 times higher than Celf1 in jejunal and colonic SMC." (PMID 28152551, 2017). "In muscular dystrophies, mutated Dmpk mRNAs containing long CUG repeats induce CELF1 expression, leading to the suppression of MBNL1." (PMID 28152551, 2017). "DMPK functions to protect against muscular dystrophies by balancing the antagonistic activities of two RNA-binding proteins, CUGBP1 (CELF1) and MBNL1, whose dysregulation can lead to abnormal splicing of ion channels, including the voltage-gated calcium channel." (PMID 28152551, 2017). "It seems possible therefore that the mis-regulation of CELF1 in DM1 may contribute to pathogenesis by disrupting secretion of ECM and/or other extracellular proteins resulting in a muscular dystrophy despite the fact that the gene affected in DM1, DMPK, does not encode an ECM component." (PMID 28129347, 2017).
Obesity (4 papers, 2013 to 2026). Accumulation of substantial excess body fat. "Population genetic studies have established a direct link between variations in the CELF1 gene locus and an increased risk of obesity, positioning it as a key player in the disease’s pathophysiology." (PMID 41596407, 2026). "First, CELF1 expression is significantly reduced in subcutaneous fat of individuals with obesity and negatively correlates with BMI." (PMID 41596407, 2026).
diabetic cardiomyopathy (3 papers, 2016 to 2025). Diabetic cardiomyopathy is a disorder of the heart muscle in people with diabetes. "Up-regulation of CELF1 and changes in CELF-mediated splicing have also recently been implicated in diabetic cardiomyopathy." (PMID 26866591, 2016). "CELF1 is also up-regulated in a mouse model of diabetic cardiomyopathy, and has been proposed to similarly reactivate fetal alternative splicing in the diabetic heart." (PMID 26866591, 2016). "Besides, another study indicated that CUG-BP (also known as CELF1)/RBFox2 can be phosphorylated and up-regulated by activating PKC signaling in diabetic heart, which in turn alters the AS of gene and contribute to diabetic cardiomyopathy pathogenesis." (PMID 36277184, 2022).
oral cancer (3 papers, 2015 to 2018). "Using next generation sequencing (RNA-seq) we identified 1283 CELF1 regulated mRNAs in oral cancer cells associated with cell proliferation, angiogenesis and signal transduction." (PMID 26498364, 2015). "Therefore, to investigate the role of CELF1 in cancer associated alternative splicing, we used our RNA-seq transcriptome data to analyze alternative splice variants in sicontrol and siCELF1 transfected oral cancer cells." (PMID 26498364, 2015). "RNA-sequencing identified 1283 mRNA transcripts involved in various cellular pathologies and are differentially regulated due to overexpression of CELF1 and promoted alternative splicing in oral cancer cells." (PMID 29728583, 2018). "Overexpression of CELF1 was reported to prevent apoptosis by destabilizing pro-apoptotic mRNAs in oral cancer cells." (PMID 29728583, 2018). "We have also measured mRNA expression of the 15 significant targets in UMSCC-11B and SCC-15 oral cancer cell lines treated with CELF1 siRNA, using qRT-PCR." (PMID 26498364, 2015). "In this study, utilizing next generation sequencing in CELF1 depleted oral cancer cells, we identified mRNA targets that were both directly and indirectly controlled by CELF1." (PMID 26498364, 2015). "To elucidate the post-transcriptional regulation of CELF1 in oral cancer progression, we sequenced total RNA isolated from UMSCC-74B cells 48 hrs post transfection with control or siRNA targeting CELF1." (PMID 26498364, 2015). "Altogether, these data provided a comprehensive view of the CELF1 mRNA regulatory network in oral cancer and suggests that CELF1 and/or its target mRNAs are viable candidates for therapeutic intervention." (PMID 26498364, 2015). "In this report, we demonstrated that in oral cancer cells CELF1 controls the expression of 1283 mRNAs that were enriched in biological terms associated with cell proliferation and apoptosis, which was not surprising." (PMID 26498364, 2015). "Querying the TCGA HNSCC dataset we identified 8 potential mRNA targets (ESM1, KLF4, IL8, CCL20, IL24, CCNA1, TIMP4 and MMP1) from our validated 20 mRNA panel, which were aberrantly expressed in HNSCC and controlled by CELF1 in oral cancer cells." (PMID 26498364, 2015). "Therefore, we were able to comprehensively assess CELF1-mediated gene expression patterns in oral cancer cells." (PMID 26498364, 2015). "Gene ontology (GO) molecular function enrichment analysis using the cytoscape plugins Cluepedia and ClueGO, revealed that the CELF1 regulated mRNAs in oral cancer cells are involved in cellular activities that include RNA binding, receptor binding and kinase activity." (PMID 26498364, 2015). "Our previous report indicated that CELF1 accumulation correlated with cancer stage, suggesting that CELF1 may play an important role in oral cancer progression." (PMID 26498364, 2015). "Thus, our RNA-seq data is an adequate representation of the CELF1 regulated transcriptome in oral cancer cells." (PMID 26498364, 2015). "Moreover, reduction of CELF1 in oral cancer cells decreased cell growth and increased apoptosis, suggesting that CELF1 may be an important regulator of oral cancer progression." (PMID 26498364, 2015). "Therefore, we set out to identify the CELF1 regulatory network in oral cancer cells." (PMID 26498364, 2015). "Intriguingly, CELF1 is a broadly expressed member of the CUGBP ELAV-like family of RBPs and is overexpressed in multiple cancers including lung and oral cancer." (PMID 26498364, 2015).
acute myelogenous leukemia (2 papers, 2022 to 2025). "RBM25, TARDBP, and CELF1 were found to be correlated with many CASEs, among which RBM25 was thought to inhibit the progression of acute myelogenous leukemia by affecting MYC activity." (PMID 35126520, 2022).
acute myocardial infarction (2 papers, 2022). Necrosis of the myocardium, as a result of interruption of the blood supply to the area. "Using the acute myocardial infarction (AMI) animal model, it was found that the expression level of CUG triple repeat RNA binding protein 1 CUGBP1))/CELF1 in the heart damaged by AMI was reduced." (PMID 36178367, 2022).
cutaneous melanoma (2 papers, 2017 to 2024). A primary melanoma arising from atypical melanocytes in the skin. "CELF1 has been implicated as a key driver in skin melanoma and functions as an oncogene by amplifying the signaling effect of DEK SpecificallyCELF1 achieves this by binding to the GU-rich 3' UTR region of DEK mRNA, which leads to an extended half-life of DEK mRNA." (PMID 38443798, 2024). "Transcriptomic, proteomic, and RNA-immunoprecipitation studies, together with loss-of-function analyses and evaluation of patient prognosis, confirmed the relevance of CELF1 as a driver of cutaneous melanoma, with the oncogene DEK as a signal amplifier." (PMID 29269732, 2017). "Therefore, we questioned to which extent the CELF1–DEK correlation found here in cutaneous melanomas was a generalized feature of malignant cells." (PMID 29269732, 2017).
fragile X-associated tremor/ataxia syndrome (2 papers, 2010 to 2017). Fragile X-associated tremor/ataxia syndrome (FXTAS) is a rare neurodegenerative disorder characterized by adult-onset progressive intention tremor and gait ataxia. "In addition, overexpression of CELF1 suppressed the neurodegenerative eye phenotype in a transgenic fly model of fragile X-associated tremor/ataxia syndrome (FXTAS)." (PMID 29056900, 2017).
glaucoma (2 papers, 2022 to 2023). Increased pressure in the eyeball due to obstruction of the outflow of aqueous humor. "As both MYBPC3 and CELF1 were found to play a role in other cells and diseases, they provide a good reference for further studies on AD and glaucoma." (PMID 36118709, 2022).
heart failure (2 papers, 2013 to 2020). Inability of the heart to pump blood at an adequate rate to meet tissue metabolic requirements. "The upregulated CELF1 in adult cardiomyocytes led to arrhythmia, dilated cardiomyopathy, and eventual heart failure." (PMID 32466553, 2020). "Additionally, mouse models have shown that CELF1 overexpression in the heart results in splicing defects, which leads to cardiomyopathy and ultimately cardiac failure." (PMID 32466553, 2020).